STAT3 (signal transducer and activator of transcription 3)
Diseases named in the same sentence as STAT3 in open-access papers (continued):
Sharing a sentence is not in itself a finding about the gene and the disease.
colitis (continued). "STAT3 induces the expression of genes important for cell cycle progression (such as cyclinD1 and PCNA) as well as suppression of apoptosis (Bcl-XL, Bcl-2, and Mcl-1), eventually promoting cell survival and proliferation during colitis-associated tumorigenesis." (PMID 23379788, 2013). "Moreover, activated STAT3 is critical both for protection against colitis and for the restoration of intestinal integrity during colitis." (PMID 22675454, 2012). "Therefore, further preclinical colitis studies need to be performed with more specific dual inhibitors of NF-κB and STAT3, in order to gauge the clinical potential of this pharmacological approach for IBD." (PMID 22506136, 2012). "Elevated S100A9 expression in CECs mediated by an IL-6/STAT3 signaling cascade may play an important role in the development of colitis." (PMID 22962574, 2012). "Inactivation of STAT3 may contribute to colitis and clinical manifestations of Ebola virus infection like abdominal pain and bloody stools." (PMID 22383882, 2012). "Thus, systemic administration of an IKKβ-specific inhibitor reduced Stat3 activation and IL6-target gene expression and ameliorated disease in colitis-prone IL10-deficient mice." (PMID 20478049, 2010). "Accordingly, mice lacking il10 or harbouring Stat3-deficient macrophages are characterized by excessive cytokine release and develop colitis." (PMID 20478049, 2010). "Moreover, activation of S1PR1 leads to persistent activation of signal transducer and activator of transcription 3 (STAT3) and nuclear factor kappa B (NF-κB) which are implicated in the development of chronic intestinal inflammation and colitis-associated colorectal cancer." (PMID 40715217, 2025). "It has been found that the absence of the STAT–3 gene in mouse intestinal epithelial cells significantly alleviates the worsening of colitis caused by P2Y13 (G protein–coupled receptor) activation, suggesting that STAT–3 may be a key target for the treatment of ulcerative colitis." (PMID 40005889, 2025). "Animal experiments show that the knockdown of Zdhhc7 or inhibition of APT2 to interrupt the palmitoylation-depalmitoylation cycle alleviates the symptoms of colitis in a mouse model, suggesting that the STAT3 palmitoylation cycle and its regulatory enzymes may be new therapeutic targets for colitis." (PMID 40959086, 2025). "Another study showed that deficiency of the Rela/Stat3-CYP enzyme pathway in mouse liver led to a decrease in primary BAs and ameliorated colitis, suggesting that inhibitors of this pathway could offer a novel mechanism to control inflammation in IBD through the gut–liver axis." (PMID 39767816, 2024). "IFN-γ directly targets and inhibits signal transducer and activator of transcription 3 (STAT3) by upregulating the expression of miR-125a and miR-125b, thereby inhibiting T helper 17 (Th17) differentiation and enhancing the ability of BMMSCs-Exo to improve the colitis phenotype in mice." (PMID 38994350, 2024). "Thus, our findings substantiate the hypothesis that LCFAs exacerbate colitis through the activation of the STAT3 pathway." (PMID 38233383, 2024). "In addition, extracts of Rubia cordifolia and L. riboside, as novel prebiotics, have been shown to alleviate the symptoms of colitis in DSS mice by inhibiting the IL-6/JAK2/STAT3 inflammatory pathway and NLRP3 inflammatory vesicles, restoring Th1/Th2 and Th17/Treg balance, among other mechanisms." (PMID 37389342, 2023). "Studies on STAT3 report its involvement in various autoimmune disorders, including inflammatory bowel disease (IBD), in which its activation in acquired immunity results in a pathogenic role in colitis, whereas its activation in innate immunity results in a suppression of colitis." (PMID 37994325, 2023). "Thus, both the activation of p65 and STAT3 are restrained by MIR31 in colitis." (PMID 36590397, 2022).
colitis (continued). "This work indicates a critical contribution of STAT3 signaling in COL1+ CAFs, suggesting that the blockade of STAT3 activation in type I collagen-expressing fibroblasts could serve as promising therapeutic targets in colitis-associated CRC." (PMID 35326623, 2022). "To further verify our hypothesis that activation of P2RY13 may promote the development of colitis through the IL-6/STAT3 signaling pathway, we generated intestinal epithelial cells STAT3 conditional knockout (STAT3△IEC) mouse strain as described in the Materials and Methods." (PMID 35982893, 2022). "Thus, Bp7 and Bp8 ameliorate colitis by activating the PPARγ/STAT3 pathway." (PMID 35681301, 2022). "Hence, STAT3 in these two cell lineages was protective against colitis." (PMID 36498596, 2022). "Notably, after 28 days, mice with colitis induced by STAT3 GOF T cells had a significant reduction in the frequency of peripherally induced Tregs (pTregs) in the MLNs and intestinal lamina propria, suggesting decreased formation of pTregs in vivo, which was consistent with the in vitro data." (PMID 36136607, 2022). "IL-17A was shown to be a key cytokine in colitis, further supporting our hypothesis that the increase in IL-17A secretion by CD5-deficient T cells, secondary to increased Stat3 phosphorylation, is causal for the disease phenotypes we observed in CD5 KD NOD mice." (PMID 35720357, 2022). "The main finding of our study was the observed reduction in JAK2/STAT3 phosphorylation after MN treatment, indicating that inhibition of the JAK and STAT pathways may be involved in MN treatment of colitis, which is associated with pro-inflammatory cytokine gene expression." (PMID 36312760, 2022). "Since the STAT3 and ERK1/2 signaling pathways are downstream of EGFR, we quantified the transcript expression of Egfr and all 7 known EGFR ligands — Ereg, Areg, Egf, Hbegf, Tgfa, Epgn, and Btc — in colitis-associated tumors from Phd2+/– and WT control mice by qRT-PCR." (PMID 36509284, 2022). "The BTWD has been found to also alleviate inflammation in the mouse model of colitis, which may be related to a variety of signaling pathways, including the modulation of intestinal microflora and inflammatory signaling pathways, such as IL-6/STAT3." (PMID 34539797, 2021). "STAT3 phosphorylation by IL-10, which is produced in a wide range of innate leukocytes (macrophages, neutrophils, and dendritic cells), might play a role in preventing the disease in experimental colitis models." (PMID 34068714, 2021). "Increased IL-22 secretion causes signal transducer and activator of transcription 3 (STAT3) phosphorylation, which ultimately leads to faster proliferation of intestinal epithelial cells (IECs), contributing to the recovery of damaged intestinal mucosa following DSS-induced colitis." (PMID 34073220, 2021). "Likewise, mice with complete genetic Stat3 ablation driven by the RosaCreERT2 promoter (RosaCreERT2;Stat3fl/fl) reached the experimental endpoint by day 4, indicating that the levels of cellular STAT3 activity inversely correlate with colitis severity." (PMID 33673239, 2021). "In this study, it was observed that CdtB can up-regulate Jak2/Stat3 phosphorylation, suggesting that the promotion of Jak/Stat pathway may be involved in the effect of H. hepaticus CdtB on colitis, which is related to the expression of proinflammatory cytokine-related genes." (PMID 33777833, 2021). "Furthermore, some studies have been published recently, describing ETBF as a trigger for chronic Stat3/IL-17-driven colitis which is IL-17 dependent and induces T17 colitis and tumorogenesis through the secretion of the metalloproteinase Bft and other associated factors." (PMID 32685120, 2020).
colitis (continued). "In the present study, we showed that QD exhibits a potent anticolitis effect in mice with experimental colitis by suppressing colonic oxidative stress and restraining colonic Th1/Th17 responses, which are associated with activating AMPK/Nrf-2 signals and inhibiting STAT1/STAT3 signals, respectively." (PMID 31737179, 2019). "Defective macrophage differentiation and IL-10-dependent STAT3 phosphorylation in DOCK8-deficient macrophages further strengthens our conclusion that WASP, together with DOCK8, regulates anti-inflammatory macrophage function and protects from colitis development." (PMID 29725003, 2018). "Furthermore, some studies have been published recently, describing ETBF as a trigger for chronic Stat3/IL-17-driven colitis which is IL-17 dependent and induces Th17 colitis and tumorogenesis through the secretion of the metalloproteinase Bft and other associated factors." (PMID 28924454, 2017). "Thus, we can hypothesize that the currently observed anti-inflammatory effect of hCTS seen during the reactivation of colitis occurs through the downregulation of the M1 population and potentially through the activation of STAT-3 phosphorylation." (PMID 28871257, 2017). "As colon biopsies and sera from IBD patients have increased concentrations of TNF-α and IL-6, the suppressive effect of GpS on TNF-α and IL-6 production in the colons of colitis mice may also indicate the potential inhibitory effect of GpS on NF-κB and STAT3 signaling." (PMID 29152090, 2017). "Moreover, hyperactivation of STAT3 in mice missing SOCS3 activity led to severer colitis." (PMID 26938566, 2016). "It was demonstrated that the level of activated STAT3 was higher in intestinal epithelial cells from patients with active ulcerative colitis compared with that in patients with inactive disease or healthy controls, and this level was positively correlated with the severity of colitis." (PMID 27574508, 2016). "Thus, STAT3 is an important target in DSS induced colitis therapy." (PMID 27258062, 2016). "Moreover, the IL-6/STAT3 pathway is an important target in DSS induced colitis therapy." (PMID 27258062, 2016). "Furthermore, a direct link between colitis induction by enterotoxigenic Bacteroides fragilis, a commensal bacterium of the intestinal flora, and tumor formation via STAT3 could be established." (PMID 26938566, 2016). "Several studies indicated that STAT3 activation plays distinctlydifferent roles between innate and acquired immune responses in colitis, that is,activation of STAT3 in innate immune cells enhances mucosal barrier function andSTAT3 activation in T-cells exacerbates colitis." (PMID 24885273, 2014). "Indeed, STAT3 activation was markedly elevated in the CECs from mice with DSS-induced colitis." (PMID 22962574, 2012). "The mechanism for this resistance to colitis may be attributable to increased IL-22/JAK2/STAT3 signaling, since recent studies indicate that activation of STAT3 within the intestinal epithelium plays an important role in mucosal tissue repair through secretion of IL-22 from innate immune cells." (PMID 22675454, 2012). "Notably, mice lacking IL-6 (IL-6 null) or STAT3 in IECs show reduced CAC tumorigenesis but develop more severe DSS-induced colitis, with pronounced colonic ulceration and body weight loss, than do wild-type counterparts." (PMID 22962574, 2012). "In DSS-induced colitis in mice, AED at 10 μg/mL suppressed pro-inflammatory cytokine production and inhibited JAK1/STAT3 signaling." (PMID 42279653, 2026). "This review indicated that IN alleviates colitis by activating AhR signaling and inhibiting STAT1/STAT3 signals and IL-10." (PMID 40756994, 2025). "Xiaoying Yang demonstrated that CGA alleviates renal fibrosis by inhibiting JAK2/STAT3 signal transduction; Qingqing Li further supported this mechanism in murine models of colitis, where CGA treatment resulted in suppressed STAT3 expression." (PMID 41369337, 2025).
colitis (continued). "KO of either C/EBPβ or STAT3 in colon epithelial cells abolished the protective functions of IL-17A and IL-22 against DSS-induced colitis." (PMID 40749055, 2025). "Early DFO-induced iron depletion was able to maintain the p-STAT3 and p-ERK1/2 signaling pathways within the colonic epithelium at the early phase of colitis, but late DFO treatment inhibited the activity of these two pathways." (PMID 39949764, 2025). "STAT3 and NF-κB upregulated the expression of arginase 1 (ARG1) and inducible nitric oxide synthase (iNOS), the main suppressors of MDSCs in murine colitis induced by dinitrobenzene sulfonic acid (DNB) or DSS." (PMID 40244120, 2025). "In the present study, colonic levels of IL‐6 and STAT3 were significantly decreased in the PTX‐treated, mesalamine‐treated, and combination‐treated groups compared to the colitis group." (PMID 40387460, 2025). "It was found that colonic epithelium had a significant decrease of both p-STAT3 and p-ERK1/2 at day 5 after DSS treatment, the administration of DFO during the early stage of colitis reserved the expression of p-STAT3 and p-ERK1/2." (PMID 39949764, 2025). "Circadian disruption in the gut epithelium led to worse colitis, reduced SCFA-producing bacteria, and increased pro-inflammatory STAT3 signaling." (PMID 41425940, 2025). "For instance, Faecalibacterium prausnitzii is demonstrated to alleviate colitis and enhance the tumor‐suppressive effects of specific immune checkpoint blockade, and Bacteroides fragilis could promote colonic mucosa regeneration in colitis by activating STAT3 signaling pathway." (PMID 39803248, 2025). "In this study, we evaluated the therapeutic potential of two novel selective STAT3 small-molecule inhibitors, HCB-5300 and HCB-5400, in a DSS-induced colitis model." (PMID 41465408, 2025). "Mechanistic evidence specifically indicates that, in the TNBS-induced colitis model, GPR15 promotes STAT3-dependent Th17 activation and IL-17-mediated pathology." (PMID 40957881, 2025). "Mechanistically, LCFAs upregulate the signal transducer and activator of transcription-3 (STAT3) pathway in the inflammatory model, and STAT3 knockout effectively counters the pro-inflammatory effects of LCFAs on colitis." (PMID 38233383, 2024). "Flow cytometry analysis showed increased p-STAT3 expression in CLP DCs and CD103+ DC subsets after Akk treatment in colitis mice." (PMID 39734222, 2024). "In mice, Western blotting revealed that administration of HPAD or HSAD in colitis-induced mice led to an increase in p-STAT3Y705 expression, while the total STAT3 level remained unchanged." (PMID 38233383, 2024). "IL-6-induced signal transducer and activator of transcription 3 (STAT3) signaling plays a key role in the differentiation of CD4+ T cells to Tregs or Th17 cells, which determines the quiescence or the development of colonic inflammation." (PMID 38257292, 2024). "We aimed to investigate the anti-colitis efficacy of CSCC and explore the mechanism by which GPR43 inhibits the NLRP3/STAT3 signaling pathway, thereby mediating the protective effects of CSCC on the intestinal barrier." (PMID 39329121, 2024). "In a study on DSS-induced colitis in mice, CSCC exhibited powerful anti-inflammatory effects by inhibiting the JNK1/STAT3 signaling pathway, reducing the levels of pro-inflammatory cytokines TNF-α, IL-1β, and IL-17." (PMID 39329121, 2024). "The hepatic RelA/STAT3-CYP enzyme pathway increased primary BAs and exacerbated DSS-induced colitis." (PMID 39767816, 2024). "DSS-induced colitis was alleviated by Gegen Qinlian decoction, which was mediated by the suppression of IL-6/JAK2/STAT3 signaling." (PMID 39133435, 2024). "Formononetin can reduce the expression of IL-6 to alleviate colitis symptoms in mice and inhibit JAK2/STAT3 signaling pathway transduction to protect against cerebral ischemia reperfusion injury." (PMID 39318778, 2024).
colitis (continued). "Compared with the control group, colitis dramatically upregulated the expression of phospho-JAK2 and phospho-STAT3 in the colon tissues, while the UTI treatment markedly inhibited the phosphorylation of JAK2 and STAT3." (PMID 38397811, 2024). "Recent findings have indicated that TAK‐242 dose‐dependently alleviated DSS‐induced colitis symptoms and colonic lesions by downregulating TLR4 and JAK2/STAT3 mRNA and protein expression and increasing JAK2/STAT3 phosphorylation." (PMID 38676295, 2024). "Our results showed that the broad-spectrum palmitoylation inhibitor 2-BP downregulated palmitoylated STAT3 in colitis cell models, while the selective APT2 inhibitor ML349 upregulated palmitoylated STAT3." (PMID 38233383, 2024). "Wild-type mice also had higher expression of genes associated with inflammatory cytokines (Il6 and Il22) and transcription factors downstream of both toll-like receptor and PAR2 signaling (Stat3 and Bcl6), compared to R38E-PAR2 mice after colitis." (PMID 39171684, 2024). "SASP can reduce oxidative stress and the inflammatory response in TNBS-induced colitis model rats by reducing the expression of TNF-α and IL-1β and inhibiting IL-6/JAK2/STAT3 signal transduction." (PMID 39318778, 2024). "For example, chronic stress is known to trigger inflammatory responses, disrupt gut microbiota, activate IL-6/STAT3 signaling, and enhance immune responses, including DSS-induced colitis." (PMID 39720595, 2024). "Moreover, considering that STAT3 is activated in acute colitis, and its expression gradually disappears during the chronic stage of the disease, here we speculate that B. fragilis motivates STAT3 signaling to facilitate colonic mucosa regeneration at the acute phase of DSS-induced colitis." (PMID 37114045, 2023). "For instance, in TH17 cells, the palmitoylation of STAT3 mediated by ZDHHC7 and the depalmitoylation of p-STAT3 by acylprotein thioesterase 2 (APT2) create a cycle that enhances the activation of STAT3 signaling pathway and promotes colitis." (PMID 37161425, 2023). "Ligliptin activated the AMPK-SIRT1-PGC-1α pathway and inhibited the JAK2/STAT3 signaling pathway, downregulated TNF-α, IL-6 and NF-κB p65, and upregulated the anti-inflammatory cytokine IL-10, reducing the severity of colitis." (PMID 37483618, 2023). "These considerations are further supported by the result that IL-6 reduces STAT3 expression in intestinal epithelial cells (IECs) and increases the severity of DSS-induced colitis in IL-6−/− mice." (PMID 36713833, 2023). "Together, these results indicate that STAT3 is a positive regulator for DC maturation and function, and CD73-expressing ERCs can manipulate STAT3 activity in DCs to control the colitis progress." (PMID 37180168, 2023). "Immunohistochemistry and Western blot analysis showed that the levels of STAT3 phosphorylation and COX-2 protein expression in the colitis group were significantly increased, and the levels of these two proteins were decreased after POLP treatment." (PMID 37375369, 2023). "It is the strength of this study that the roles of overactivated NF-κB and STAT3 on inducing ferroptosis in IECs and elevated FGL1 on enhancing colitis are uncovered." (PMID 37153794, 2023). "In conclusion, POLP can exert its anti-inflammatory effect by regulating the IL6/STAT3/COX-2 pathway and can effectively treat colitis." (PMID 37375369, 2023). "During colitis with intact KLF5, IL-22 helps signal regeneration in the intestinal epithelium through p-STAT3 signaling." (PMID 35393949, 2022). "Nuclear factor (erythroid-derived 2)-like 2 (Nrf2), Signal Transducer and Activator of Transcription 3 (STAT3), and Phase II enzyme UDP-glucuronosyltransferase (UGT) were involved in the protective effect of SFN against DSS-induced colitis." (PMID 35832050, 2022). "It has been proven that STAT3 is an effective target for inhibiting TH17 cell differentiation and attenuating colitis in IBD mouse models." (PMID 36532769, 2022).